PARP11 (poly(ADP-ribose) polymerase family member 11)
Description:
Mono-ADP-ribosyltransferase that mediates mono-ADP-ribosylation of target proteins. Plays a role in nuclear envelope stability and nuclear remodeling during spermiogenesis (By similarity). Inhibits the type I interferon activated signaling pathway. Mechanistically, mono-ADP-ribosylates beta-TrCP/BTRC to promote IFNAR1 ubiquitination and protect BTRC from ubiquitin-proteasome degradation. Additionally, acts as an antiviral factor by cooperating with PARP12 to suppress Zika virus replication, independent of IFNAR1 regulation or intrinsic PARP enzymatic activity. Instead, facilitates the degradation of viral NS1 and NS3 proteins, potentially disrupting viral replication.
Synonyms: ARTD11; C12orf6; MIB006
Tractability: Small molecule: a high-quality ligand is known. PROTAC: a small molecule that binds it is known.
Target class: Enzyme; Transferase
Gene: Protein-coding gene on chromosome 12 (3,791,047 to 3,873,448, reverse strand). Ensembl gene ENSG00000111224.
Subcellular location: Nucleus, nuclear pore complex
Subcellular location (Human Protein Atlas): Nuclear bodies; Cytosol; Nucleoplasm
Gene Ontology:
Molecular function: NAD+ poly-ADP-ribosyltransferase activity; NAD+-protein mono-ADP-ribosyltransferase activity; NAD+-protein-aspartate ADP-ribosyltransferase activity; NAD+-protein-cysteine ADP-ribosyltransferase activity; NAD+-protein-glutamate ADP-ribosyltransferase activity; NAD+-protein-lysine ADP-ribosyltransferase activity
Biological process: protein auto-ADP-ribosylation
Cellular component: nuclear body; nuclear envelope; nucleoplasm; nucleus; nuclear pore
Genetic constraint (gnomAD): Loss-of-function variants: 29 observed, 37.27 expected, observed/expected ratio (o/e) 0.78, 90% interval 0.58 to 1.06. The upper end of that interval is the gene's LOEUF score, 1.06, which puts it in group 4 of 6, group 1 being the genes least tolerant of losing a copy. Missense variants: 330 observed, 391.11 expected, observed/expected ratio (o/e) 0.84, 90% interval 0.77 to 0.92. Synonymous variants: 123 observed, 124.14 expected, observed/expected ratio (o/e) 0.99, 90% interval 0.86 to 1.15.
Homologues: Orthologues: macaque PARP11 (99% identical), chimpanzee PARP11 (99% identical), rabbit PARP11 (96% identical), pig PARP11 (94% identical), dog PARP11 (93% identical), mouse Parp11 (93% identical), rat Parp11 (93% identical), guinea pig PARP11 (91% identical), tropical clawed frog parp11 (62% identical), zebrafish parp11 (37% identical). Paralogues in human: PARP12 (35% identical), TIPARP (30% identical), ZC3HAV1 (27% identical), PARP14 (25% identical), PARP15 (22% identical), PARP10 (21% identical), PARP9 (14% identical), ZC3HAV1L (1% identical).
Diseases named in the same sentence as PARP11 in open-access papers:
PARP11 is named in the same sentence as 16 diseases in open-access papers, as found by Europe PMC text mining. Sharing a sentence is not in itself a finding about the gene and the disease. The quoted sentences say what the papers report.
viral infection (5 papers, 2021 to 2024). "PARP11 expression is significantly up-regulated during virus infection, including VSV, HSV-1 and IAV." (PMID 34871367, 2021). "Strikingly, viral infection promotes the expression of PARP11 (ARTD11), which in turn mono-ADP-ribosylates the ubiquitin E3 ligase β-TrCP." (PMID 34725336, 2021). "Besides, the disturbance caused by PARP11-KO occurred in the transcription process of the immediate-early gene IE180, indicating PARP11 works on PRV replication at the early stage of viral infection." (PMID 39445214, 2024). "PARP1–3 are activated by DNA damage, whereas the mono-ARTs PARP10, PARP11 and PARP12 are upregulated during viral infection leading to translational shut-down." (PMID 36018800, 2022). "Importantly, the inhibitory effects of rucaparib on viral infection and enhanced ISG expression are largely diminished by PARP11 knockdown." (PMID 34871367, 2021). "Instead, PARP11 interacted and cooperated with PARP12 in suppressing ZIKV replication, which provided a new insight on understanding the mechanisms responsible for different PARP family members in viral infection." (PMID 34187568, 2021).
teratozoospermia (3 papers, 2021 to 2025). "Deletion of the PARP11 gene affects the shape of the cell nucleus and causes the formation of abnormally shaped fertilization-incompetent sperm, resulting in teratozoospermia and male infertility in mice." (PMID 37685979, 2023). "PARP11 was reported as a novel enzyme important for proper sperm head shaping and a potential factor involved in idiopathic mammalian teratozoospermia." (PMID 34187568, 2021).
ZIKV infection (3 papers, 2021 to 2025). "Another study demonstrated that PARP11 cooperated with PARP12 in restricting ZIKV infection through enhancing NS1 and NS3 degradation, indicating PARP11 was an anti-virus factor in ZIKV infection." (PMID 39445214, 2024). "PARP12 can suppress Zika virus infection through degradation of NS1 and NS3 viral proteins and cooperation with PARP11." (PMID 39445214, 2024). "In this work, we found that PARP11 was up-regulated in response to IFN-I stimulation and ZIKV infection, and acted as an anti-ZIKV ISG." (PMID 34187568, 2021). "Similar to exogenous IFN treatment, ZIKV infection also induced PARP11 mRNA and protein expressions in WT but not in IFNAR1−/− A549 cells." (PMID 34187568, 2021). "Both mRNA and protein levels of PARP11 were induced in WT but not IFNAR1−/− cells in response to IFNα or IFNβ stimulation and ZIKV infection." (PMID 34187568, 2021).
breast carcinoma (1 paper, 2022). "In reviewing the literature, no data were found on the association of breast cancer with PCGF1, RNF123, GRWD1, USP30, ATXN3L, and PARP11." (PMID 36685836, 2022).
cervical cancer (1 paper, 2025). A primary or metastatic malignant neoplasm involving the cervix. "Moreover, PARP11 seemed to have a lower specificity in lung cancer, as it also decreased significantly in colorectal cancer, and cervical cancer, while elevated in ovarian cancer." (PMID 39949782, 2025).
cryptorchidism (1 paper, 2025). The failure of one or both testes of a male fetus to descend from the abdomen into the scrotum during the late part of pregnancy. "In addition, we confirmed two key DE-FRGs, BRDT and PARP11, by integrating the DEGs associated with spermatogenesis, which were downregulated in AdMinus testes of patients with cryptorchidism." (PMID 40454210, 2025). "Overall, we deduced that BRDT and PARP11 downregulation in patients with cryptorchidism may hinder spermatogenesis, which could be used as a reference for early therapeutic strategies for patients with cryptorchidism." (PMID 40454210, 2025). "Gene Set Enrichment Analysis, ROC and IHC analyses were conducted and the results revealed that BRDT and PARP11 might play critical roles in spermatogenesis dysfunction in patients with cryptorchidism." (PMID 40454210, 2025). "In conclusion, our study revealed that BRDT and PARP11 were downregulated in AdMinus testes of cryptorchidism, which suggested that ferroptosis might play a significant role in spermatogenic dysfunction in cryptorchidism." (PMID 40454210, 2025).
glioma (1 paper, 2026). A benign or malignant brain and spinal cord tumor that arises from glial cells (astrocytes, oligodendrocytes, ependymal cells). "Among shared targets, we identify PARP11/Parp11 as a consistently up-regulated gene in glioma, which is down-regulated after MIRO1-binding compound treatment in both human and mouse gliomas." (PMID 42128668, 2026).
infection (3 papers, 2021 to 2024). The state of being infected such as from the introduction of a foreign agent such as serum, vaccine, antigenic substance or organism. "Recent data have also implicated PARP-11 as a mediator of infection." (PMID 34485381, 2021). "Overexpression in Vesicular stomatitis virus (VSV), HSV-1 and IAV infection during infection, PARP-11 MARylates the ubiquitin E3 ligase β-transducin repeat-containing protein (β-TrCP)." (PMID 34485381, 2021). "It was found that PARP11 knockout cells had a significantly higher EGFP intensity than WT cells, suggesting that PARP11 knockout promoted PRV-EGFP infection." (PMID 39445214, 2024). "To further determine whether infection of PRV was negative correlation with PARP11 expression, we knocked down endogenous PARP11 by transfecting PK-15 and LLC-PK1 cells with synthesized PARP11-specific siRNA (siPARP11) for 24 h." (PMID 39445214, 2024). "For example, SARS-CoV2 induces expression of several noncanonical PARPs – PARP-7, PARP-9, PARP-10, PARP-11, PARP-12, PARP-13 and PARP-14 were substantially upregulated following infection with the magnitude of subsequent NAD+ depletion being proportional with viral titres." (PMID 34485381, 2021).
tumor (2 papers, 2025). "PARP11 inhibitors: PARP11 is one of the most innovative regulators of the evasion of antitumor immunity and resistance to therapies in solid tumors, playing key roles in the immunosuppressive tumor microenvironment (TME)." (PMID 41463260, 2025). "Notably, PARP4, PARP7, PARP10, PARP11, and PARP15 have been clearly implicated in tumor development and progression, functioning either as oncoproteins with prognostic relevance or, in certain contexts, as tumor-suppressive factors." (PMID 41463260, 2025). "PARP9, PARP11, PARP13, PARP14, and PARP15: The remaining PARP members with MAR activity exhibit a tumor-promoting role." (PMID 41463260, 2025). "Compared to PARP1, the mechanism of PARP11 in tumor development has not been uncovered." (PMID 39949782, 2025).
cancer (1 paper, 2025). A tumor composed of atypical neoplastic, often pleomorphic cells that invade other tissues. "In the LUSC group, we can get a similar conclusion, in addition, DPP4, PARP11, and TCP11L2 were found to be positively correlation with the cancer-associated fibroblasts (CAFs) and endothelial cells." (PMID 39949782, 2025).
PARP11 also shares sentences with these, for which no sentence is quoted: male infertility (2 papers); colorectal cancer (1); lung carcinoma (1); lupus (1); melanoma (1); ovarian carcinoma (1).